IL10 (interleukin 10)
Diseases named in the same sentence as IL10 in open-access papers (continued):
Sharing a sentence is not in itself a finding about the gene and the disease.
malaria (continued). "A drastic increase in IL-10 producing CD4+ T cells was observed at the early stage as well as at later stage of infection with lethal malaria parasites, while with the non-lethal malaria parasites the frequency of IL-10 producing CD4+T cells was significantly less." (PMID 35109868, 2022). "Also, although IL-10 was not in any of the four patterns for malaria, there was a positive correlation between IL-10 and TNFα levels." (PMID 35811678, 2022). "However, the importance of IL-10+ B-cells in the regulation of immune response and immunopathology in malaria has not been explored so far to an extent." (PMID 35625397, 2022). "Elevated IL-10 levels were observed in the Malaria cases, irrespective of subtype, which may reflect reduced T cell responses and increased B-cell activity, with IL-10 serving as endocrine growth factor." (PMID 34962938, 2021). "Using a bespoke flow cytometry assay we measured intracellular IFN-γ, IL-10, IL-17A expression and phenotyped CD4+ and CD8+ T cell effector memory subsets specific to EBNA1 for eBL patients compared to two groups of healthy children with divergent malaria exposures." (PMID 34771539, 2021). "Conversely, the presence of bacteremia may also affect asymptomatic malaria infections: our findings of relatively low circulating levels of IL-10 and IFN-γ in patients with bacteremia indicate a compromised host defense against malaria and thus a less restricted malaria infection." (PMID 34177883, 2021). "Investigations of impaired immunity to non-Typhoid Salmonella (NTS) co-infections during malaria have reported that the activities of HO-1 and IL-10, which are produced during active Plasmodium infection, play an important role in the increased severity of bacterial infection." (PMID 32714882, 2020). "We conclude that higher immunization dose may not lead to better protection with the malaria vaccine as CD19+CD1dhiCD5hi B cells can downregulate ITV protection against malaria via IL-10 secretion." (PMID 32257991, 2020). "By exploring co-infection models with different bacterial pathogens during malaria, we sought to determine whether the IL-10-dependent and HO-1-dependent mechanisms were specific to NTS co-infection, or if they also play a role in malaria-related immunosuppression to other bacterial co-infections." (PMID 32714882, 2020). "Moreover, TNF-α/IL-10 ratio increased exponentially in malaria-infected donor blood, while in the noninfected donor blood, marginal elevations were recorded." (PMID 33195706, 2020). "IL-10 plays a crucial role in modulating the inflammatory response during malaria, and it is notable that even in non-parasitaemic children, of the 65 cytokines measured in plasma, IL-10 was the only cytokine observed at significantly different levels between high- and low-episode individuals." (PMID 30862316, 2019). "IL-10 is a critical immunoregulatory molecule with both positive and negative roles during malaria." (PMID 30809232, 2019). "Here, we summarize the evidence linking malaria and invasive NTS infections; describe the role of neutrophils in clearing NTS infections; review evidence for neutrophil dysfunction in malaria infections; and explore roles of heme oxygenase‐1, IL‐10, and complement in mediating this dysfunction." (PMID 30570786, 2019). "IL-6 and IL-10 levels were found to correlate positively with acute malaria in children infected with S. haematobium who developed P. falciparum malaria when compared with Schistosoma-negative children who developed malaria." (PMID 29970128, 2018). "Likewise, the role of TNF and IL-10 have been studied in the development of P. falciparum-induced anemia; however, such a role has not been observed in the development of malaria-induced thrombocytopenia." (PMID 30510885, 2018).
malaria (continued). "Prenatal exposure to malaria was significantly associated with IL-10 (P<0.05) and IFN-γ responses (P<0.05) during clinical malaria episodes, while other factors did not significantly associate with IL-10 and IFN-γ responses." (PMID 30154871, 2018). "The development of severe malaria anemia in African children may be a result of a lack of IL-10 production in response to high TNF-α concentrations." (PMID 29970128, 2018). "Experiments in which IL-10 was administered in mouse models of malaria resulted in a lower production of TNF-α and a lower incidence of experimental cerebral malaria (ECM), leading some to hypothesize that IL-10 counteracts the potentially pathological host proinflammatory response to malaria." (PMID 28122790, 2017). "Based on the distributions of the individual biomarkers in malaria positive versus negative women (peripheral diagnosis) in the test set, a scoring model using IL-10 and sTNF-RII levels was developed for predicting a malaria infection during second and third trimester." (PMID 29255607, 2017). "Severe malaria patients exhibit high levels of serum pro-inflammatory cytokines (TNF, IL-1β, IL-6, IL-8, IL-12, IFNγ) and chemokines (CCL2, CCL5, CXCL9, CXCL10), and lower levels of regulatory cytokines (IL-10, TGFβ, PGE2) compared to those with mild and asymptomatic malaria." (PMID 27792766, 2016). "Hepcidin was positively correlated with IL-6 (r = 0.4339; p = 0.0015), IL-10 (r = 0.5154; p = 0.0002), and parasitaemia (r = 0.3032; p = 0.0096) and negatively correlated with IFN-γ/IL-10 (r = −0.4369; p = 0.0017) and (TNF + IFN-γ)/IL-10 (r = −0.3776; p = 0.0075) in the mild malaria group." (PMID 26466783, 2015). "Frequencies of IFNγ/IL10 co-producing CD4+ T cells, which express the Th1 transcription factor T-bet, were significantly higher in children with ≥2 prior episodes/year compared to children with <2 episodes/year (P<0.001) and inversely correlated with duration since malaria (Rho = −0.39, P<0.001)." (PMID 24415936, 2014). "While in the context of co-infection with malaria parasites and NTS, immunoregulation by IL-10 could prevent inflammatory pathology and resulting organ damage, a clear downside of this regulation is a reduced ability to limit bacterial burden at systemic sites." (PMID 24787713, 2014). "However, it was expected that the levels of IL-10, IFN-γ, and even IL-5 presented differences between individual experiencing different number of malaria episodes due to the fact that these cytokines are also produced by cells from the adaptive immune response." (PMID 24741587, 2014). "Interestingly, although no relations were observed between the number of malaria episodes and the levels of IL-6 and IL-10, patients with higher parasitemia produced higher levels of both cytokines." (PMID 24741587, 2014). "However, in the 96 h supernatant culture, the dynamics of cytokine responses differed from those depicted on plasma assays; in presence of PvMSP-119 stimulus, higher levels of TNF were noted in supernatant 96 h culture of malaria patient’s cells while low levels of IFN-γ and IL-10 were verified." (PMID 24041406, 2013). "Therefore, the evaluation of IL-10 and ANXA1 in the individuals with malaria was performed." (PMID 24359168, 2013). "The IL-10 and TNF production capacity and the activation phenotype of monocytes and T cells were compared in samples collected from 332 Ghanaian children with non-overlapping SMA (n = 108), cerebral malaria (CM) (n = 144) or uncomplicated malaria (UM) (n = 80) syndromes." (PMID 22853732, 2012). "Consistent with this, levels of TNF-α, IL-10 and IL-6 in placental blood (but not peripheral blood) were inversely correlated with peripheral Apo-AI levels in malaria-infected primigravidae (r = −0.385, p = 0.0017, n = 67; r = −0.484, p = 0.0002, n = 62; r = −0.353, p = 0.025, n = 50 respectively)." (PMID 20098675, 2010).
malaria (continued). "In particular the impact of baseline IL-10 and TGF-beta levels on the induction of antibodies in African populations could be assessed by monitoring volunteer samples collected prior to vaccination with RTS,S and other candidate malaria vaccines." (PMID 20838432, 2010). "Moreover, it has been shown that T cells from vaccinated healthy volunteers and adults naturally exposed to malaria with MSP1-19 could produce both IFN-γ and IL-10." (PMID 20856680, 2010). "The presence of chronic schistosomiasis infection could specifically increase IL-10 and IFN-γ production in coinfected children, a cytokine production which would positively influence the production of cytophilic anti-malaria IgG1 and IgG3 isotypes, known to be protective during malaria infection." (PMID 20856680, 2010). "IL-10 may have utility in longitudinal studies, examining the burden of malaria over gestation, when the placenta is not available for microscopic analysis." (PMID 18230163, 2008). "In P. vivax infection, maternal plasmatic cytokine imbalance may have an impact on pregnancy outcomes, as indicated by the positive correlation between both IL-6 and IL-10 levels with previous exposure to malaria and parasitemia, as well as a negative correlation with gestational age at delivery." (PMID 39495782, 2024). "Moreover, the meta-analysis results showed that patients with severe malaria had a higher SMD of the IL-10 level than those with non-severe malaria in the studies performed in Asia (p = 0.02, pooled SMD: 1.20, 95% CI: 0.17–2.24, I2: 95.93%, five studies/seven sub-studies)." (PMID 36668942, 2023). "For example, compared with Kisumu participants, the relatively augmented levels of IL-10 production observed in participants from Elgeyo Marakwet could be explained by the differences in lifestyle and diet or by the absence of malaria in this high-altitude region." (PMID 37219944, 2023). "In our study, IL-4 and IL-10 concentrations were higher in patients with severe malaria than in patients with non-severe malaria, consistent with that reported by other authors; the increase in these cytokines may reflect the immune response controlling the infectious process." (PMID 36178979, 2022). "Probably, it could indicate that IL-10 may not be the sole anti-inflammatory cytokine in mediating inflammation in asymptomatic malaria and its production may be transient during asymptomatic malaria." (PMID 33281757, 2020). "Malaria is known to exert variable effects on IL-10, depending on the severity of infection (lower IL-10 in complicated cases, compared to asymptomatic subjects), but cytokine levels, including IL-10, have not been evaluated in the currently published studies on EBOV and malaria co-infection." (PMID 31547585, 2019). "Thus, although c-Maf-dependent T cell IL-10 production protected against the detrimental impact of inflammation, it had a minimal effect of the development of anti-parasitic immunity in this non-lethal, mouse malaria model." (PMID 30809232, 2019). "Therefore, these confluent events from responses to both pathogens (increased production of IL-10, CCL2 protective role in malaria, as well as combined effects of IL-4 and IL-10) could enable the host to respond properly without unbalanced inflammation." (PMID 31233500, 2019). "TNF-α, IFN-γ, IL-1, IL-6, IL-8, and IL-10 have been found in increased levels in patients with severe malaria compared to healthy controls, decreasing in convalescence to control levels, but in these studies the clinical syndromes of severe malaria were not fully described." (PMID 28122790, 2017). "To date, IL-10-producing NK cells have not been reported in the context of malaria exposure or infection, but it is certainly possible that “regulatory” NK cells might be found to contribute to healthy resolution of the inflammation associated with malaria infections." (PMID 28337195, 2017).
malaria (continued). "However, IL-10 levels alone have not been found to correlate with malaria exposure, and all of our study participants are from the same area of holoendemic malaria transmission, making it unlikely that the higher IL-10 responses are due to differential malaria-exposure between the groups." (PMID 28033393, 2016). "However, the cluster of cytokines—TGF-β, TNF-α, IL-10, and IL-1β—that differentiated CM from other falciparum malaria manifestations in Gondia could not distinguish severe malaria cases in Odisha." (PMID 26602091, 2015). "In addition, we found that children with the fewest prior episodes of malaria were significantly more likely to have malaria-specific production of TNFα without IL-10, and that the absence of this inflammatory cytokine was associated with the phenotype of asymptomatic infection." (PMID 24415936, 2014). "Although, it appears that macrophages may not be activated in natural immune response against malaria, interferon gamma(+) and IL-10(+++) secreting CD4 T cells, cytotoxic CD8 T cells, IgG secreting B cells, and NK cells are up-regulated by interferon alpha/beta in malarial infection." (PMID 24188121, 2013). "Although our study lacked malaria positive pregnant women, comparing the results to other studies in which malaria positive pregnant women were included suggests that the levels of peripheral IL-10 in the AC group were lower than pregnant women with placental malaria." (PMID 20706538, 2010). "Thus, our data strongly suggest that the percentage of IL-10-producing Th1 effector cells, rather than the cocktail of circulating cytokines, may be the most relevant biomarker of effective immunity to severe malaria." (PMID 19343213, 2009). "However, in our mouse model of subclinical malaria, the absence of mature B cells allowed us to eliminate this immune component, anti-plasmodium antibodies, from the equation, and to investigate the contribution of IL-10-producing CD4+ T cells in the regulation of subclinical malaria." (PMID 40972121, 2025). "In patients with severe malaria, platelets showed negative correlations with CXCL10, IL-6, IL-10 and IFN-γ." (PMID 36178979, 2022). "We first assessed circulating cytokine (IL-6, IL-10, TNF-α, IFN-3γ) concentrations among healthy participants with- and without asymptomatic malaria and patients with clinical malaria." (PMID 34177883, 2021). "When examining the effect of malaria control tools on cytokine levels, CBMC from women sleeping under ITN produced higher levels of IL-10 than those not using ITN." (PMID 29743113, 2018). "Children aged between 4 and 14 years with malaria and an asymptomatic S. haematobium infection were found to have significantly higher levels of IFN-γ but similar levels of IL-10 when compared to matched children without S. haematobium infection." (PMID 29970128, 2018). "Lymphocyte from control subjects not exposed to malaria showed no significant response of IL-2, TNF, IFN-γ or IL-10 production upon PvMSP1P-19 stimulation compared to the medium control." (PMID 25889175, 2015). "However, in the absence of ongoing malaria exposure, children reverted to an apparent homeostatic baseline in which IL-10 production was no longer inducible, suggesting that ongoing malaria exposure is required to maintain P. falciparum-inducible IL-10 production capacity." (PMID 24743880, 2014). "Of seven cytokines analyzed in this study, IL-6, IL-10 and IFN-γ were elevated in malaria patients sera, thrombocytopenic or not, compared to HVs." (PMID 23723981, 2013). "The assayed cytokines were detectable in the placental sera (IFN-γ, IL-12, IL-4, IL-6 and IL-10) and plasma (TNF-α) samples extracted from malaria-infected and malaria-negative olive baboons." (PMID 26623293, 2012).
malaria (continued). "Despite the lack of specificity of the T cell proliferative responses, malaria antigen-induced effector functions – immediate (24 h) IFN-γ-producing effector memory cells and cultured (day 6) IL-10 responses - were seen only in malaria-exposed subjects." (PMID 21347351, 2011). "Among malaria-infected multigravid women levels of TNF-α and IL-10 in placental blood (but not peripheral blood) were similarly inversely correlated with peripheral Apo-AI (r = −0.453, p = 0.011, n = 24; r = −0.392, p = 0.036, n = 22 respectively)." (PMID 20098675, 2010). "However, levels of TNF‐α,10 IL‐1β,16 IL‐6,8, 33 IFN‐ɣ,33 IL‐10,11, 33 and GM‐CSF27 were not different when malaria‐infected children were compared to their counterparts without the infection in previous studies." (PMID 39240033, 2024). "Whole blood from asymptomatic participants with and without positive malaria microscopy were ex-vivo stimulated with S. aureus, E. coli LPS and Salmonella Typhimurium; cytokine concentrations (TNF-α, IFN-γ, IL-1β, IL-6, IL-10) were measured on supernatants using ELISA." (PMID 34177883, 2021). "Malaria infection in the collected maternal peripheral, placental, umbilical cord samples was determined microscopically, and ELISA was used to measure the plasma levels IL-4, IL-6, IL-10, IL-17A, and INF γ in the collected positive and negative malaria samples." (PMID 33422078, 2021). "Here we found that Malawian children presenting with all forms of malaria had high IL-10-to-TNF-α and IL-10-to-IL-6 ratios, so high levels of TNF-α and IL-6 in CM could not be attributed to a lack of IL-10 response." (PMID 28122790, 2017). "PBMCs (1×106 cells/ml) from malaria infected (n=23) and non-infected (n=7) individuals were stimulated with mycoplasma free P. falciparum parasites (at a ratio of 1:5) and after three days IFN-γ, IL-10, and IL-5 were measured in supernatant." (PMID 23294670, 2013). "The spontaneous IL-10 production levels correlated neither with monocyte HLA-DR MFI nor with the percentage of pigmented monocytes in each of the SMA, CM, UM groups or when considering all malaria cases as a single group (P ≥ .18)." (PMID 22853732, 2012). "We measured plasma levels of soluble UA and inflammatory cytokines and chemokines (IL-6, IL-10, sTNFRII, MCP-1, IL-8, TNFα, IP-10, IFNγ, GM-CSF, IL-1β) in 470 Malian children presenting with uncomplicated malaria (UM), non-cerebral severe malaria (NCSM) or cerebral malaria (CM)." (PMID 23071567, 2012). "The concomitant presence of IL-10 and a higher expression of LILRB1 and LILRB2 on non-classical monocytes suggests a down regulation of the cells involved in inflammatory mechanisms and therefore a potentially decreased ability to protect the infants from malaria." (PMID 35911674, 2022). "IL-10-producing CD4+ T cells and CD20+ IgG+ B cells were increased post-vaccination regardless of the intervention, thus could not be specifically attributed to any malaria vaccine regimen." (PMID 35715803, 2022). "A study in a seasonal malaria transmission area in Kenya found no seasonal differences in the frequency of IFN-γ and IL5 ELISpot responses, but higher frequencies of ELISpot responses to IL10 and TNF during the high transmission season compared to the low transmission season." (PMID 26830334, 2016). "T cells co-producing IFNγ/IL-10 following nonspecific PMA/ionomycin stimulation were described in the context of acute malaria infection, and were also more abundant among children with uncomplicated rather than severe malaria, consistent with a role in modulating inflammation." (PMID 24415936, 2014). "The significantly increased IL-10 and variable alteration in levels of TNF and IL-1β in both malaria-negative and malaria-positive subjects with magnesium deficiency may explain the imbalance in cytokine production as a result of magnesium deficiency modulated by malaria status." (PMID 20470442, 2010).